CSNK1G2 (casein kinase 1 gamma 2)
Description:
Serine/threonine-protein kinase. Casein kinases are operationally defined by their preferential utilization of acidic proteins such as caseins as substrates. It can phosphorylate a large number of proteins. Participates in Wnt signaling (By similarity). Phosphorylates COL4A3BP/CERT, MTA1 and SMAD3. SMAD3 phosphorylation promotes its ligand-dependent ubiquitination and subsequent proteasome degradation, thus inhibiting SMAD3-mediated TGF-beta responses. Hyperphosphorylation of the serine-repeat motif of COL4A3BP/CERT leads to its inactivation by dissociation from the Golgi complex, thus down-regulating ER-to-Golgi transport of ceramide and sphingomyelin synthesis. Triggers PER1 proteasomal degradation probably through phosphorylation. Involved in brain development and vesicular trafficking and neurotransmitter releasing from small synaptic vesicles. Regulates fast synaptic transmission mediated by glutamate (By similarity). Involved in regulation of reactive oxygen species (ROS) levels.
Synonyms: CK1G2
Tractability: Small molecule: a structure with a bound ligand is known; a high-quality ligand is known; it belongs to a druggable protein family. Antibody: its Gene Ontology location is reachable by antibodies, with medium confidence. PROTAC: ubiquitination databases record sites on it; its protein half-life has been measured; a small molecule that binds it is known.
Target class: CK1 protein kinase group; Enzyme; CK1 protein kinase CK1 family; Protein Kinase; Kinase
Gene: Protein-coding gene on chromosome 19 (1,941,146 to 1,981,339, forward strand). Ensembl gene ENSG00000133275.
Subcellular location: Cytoplasm, cell cortex; Cytoplasm
Subcellular location (Human Protein Atlas): Vesicles; Cytosol
Pathways (Reactome):
Metabolism: Sphingolipid de novo biosynthesis
Signal Transduction: Disassembly of the destruction complex and recruitment of AXIN to the membrane
Gene Ontology:
Molecular function: protein binding; protein serine/threonine kinase activity; ATP binding; protein kinase activity; protein serine kinase activity
Biological process: endocytosis; positive regulation of canonical Wnt signaling pathway; protein phosphorylation; signal transduction; sphingolipid biosynthetic process
Cellular component: cytoplasm; cytosol; membrane; plasma membrane; cell cortex
Genetic constraint (gnomAD): Loss-of-function variants: 11 observed, 38.17 expected, observed/expected ratio (o/e) 0.29, 90% interval 0.18 to 0.48. The synonymous counts are far from expectation, so gnomAD's model fits this gene poorly and the ratio says little. Missense variants: 446 observed, 506.21 expected, observed/expected ratio (o/e) 0.88, 90% interval 0.81 to 0.95. Synonymous variants: 337 observed, 225.67 expected, observed/expected ratio (o/e) 1.49, 90% interval 1.37 to 1.63.
Homologues: Orthologues: chimpanzee CSNK1G2 (99% identical), dog CSNK1G2 (97% identical), pig CSNK1G2 (97% identical), mouse Csnk1g2 (95% identical), guinea pig CSNK1G2 (95% identical), rat Csnk1g2 (95% identical), zebrafish csnk1g2a (89% identical), macaque CSNK1G2 (89% identical), zebrafish csnk1g2b (88% identical), tropical clawed frog csnk1g2 (75% identical), Drosophila melanogaster gish (71% identical), Caenorhabditis elegans F59A6.4 (25% identical), and 61 more. Paralogues in human: CSNK1G3 (83% identical), CSNK1G1 (80% identical), CSNK1D (45% identical), CSNK1E (45% identical), CSNK1A1 (41% identical), CSNK1A1L (40% identical), TTBK1 (31% identical), TTBK2 (30% identical), VRK1 (26% identical), VRK2 (23% identical), CDC7 (20% identical), VRK3 (18% identical).
Diseases named in the same sentence as CSNK1G2 in open-access papers:
CSNK1G2 is named in the same sentence as 11 diseases in open-access papers, as found by Europe PMC text mining. Sharing a sentence is not in itself a finding about the gene and the disease. The quoted sentences say what the papers report.
breast carcinoma (2 papers, 2021 to 2025). "The CK1 inhibitor, D4476, partly mimicked the CSNK1G2 knockdown effect in ER+ breast cancer cells, but with a broader repression ranging from PI3K/AKT/mTOR/S6K to ERK signaling." (PMID 33861751, 2021). "As presented by the expression of CD44/CD24 and tumor sphere formation in MCF-7 and MDA-MB-231, CSNK1G2 also affected the expression of breast stem cell-markers only in ER+ breast cancer cells." (PMID 33861751, 2021). "We report the function of CSNK1G2 in breast cancer cells in TAM sensitivity, specifically comparing its effects in ER+ and in ER- breast cancer cells." (PMID 33861751, 2021). "ER+ (MCF-7) and ER- (MDA-MB-231) human breast cancer cells seeded onto a 6-well ultra-low adherent plate were treated with 1 μM TAM after silencing CSNK1G2, and gene-targeting effect was quantified by real-time PCR for CSNK1G2." (PMID 33861751, 2021). "Although attenuation of ERK signal was only seen in ER- breast cancer cells, it is interesting that CSNK1G2 can target both PI3K/AKT/mTOR/S6K and ERK signal pathways depending on the characteristics of hormone receptor subtypes." (PMID 33861751, 2021). "Furthermore, when we examined the expression of cellular signal molecules, D4476 reproduced many of the effects of CSNK1G2 on the PI3K/AKT/mTOR signaling system in breast cancer cells." (PMID 33861751, 2021). "In addition, tumor sphere formation and expression of breast stem cell marker genes such as CD44/CD2 were greatly inhibited by CSNK1G2 knockdown in ER+ breast cancer cells." (PMID 33861751, 2021). "As mTOR is a downstream effector in the PI3K and AKT signaling pathways, we determined whether mTOR activity was altered by modulation of CSNK1G2 in breast cancer cells." (PMID 33861751, 2021). "However, overexpression of ERα in ER- MDA-MB-231 cells using GFP-ERα plasmid DNA completely reproduced the CSNK1G2 silencing-induced cytotoxic effects of ER+ breast cancer cells." (PMID 33861751, 2021). "Collectively, these results suggest that CSNK1G2 plays a key role in sensitizing TAM toxicity in ER+ and ER- breast cancer cells via differently regulating PI3K/AKT/mTOR/S6K and ERK signaling." (PMID 33861751, 2021). "From the screening, casein kinase 1 gamma 2 (CSNK1G2), a serine-/threonine protein kinase, was the most sensitive target to TAM with a significant cytotoxicity in estrogen receptor-positive (ER+) breast cancer cells but with only a slight toxicity in the case of ER- cells." (PMID 33861751, 2021). "Taken together, our results reveal a unique action mechanism of CSNK1G2 on PI3K/AKT/mTOR/S6K and ERK signaling pathways in breast cancer cells and provide insight into how the target selectively controls and contributes to cell survival in different human breast cancer cell types." (PMID 33861751, 2021). "TAM (1 μM) significantly reduced the number of formed tumor spheres by approximately 40% in ER+ breast cancer cells, whereas CSNK1G2 silencing itself did not alter the formation of ER+-MCF-7 tumor spheres." (PMID 33861751, 2021). "However, CSNK1G2 knockdown significantly inhibited PI3K activity; these results were also reproduced in the ER- breast cancer cells with less significant reduction." (PMID 33861751, 2021). "We here observe that, in breast cancer cells, CSNK1G2-silenced cells lead to the suppression of not only PI3K/AKT/mTOR/S6K but also ERK." (PMID 33861751, 2021). "However, this CSNK1G2 silencing-induced effect was not shown in ER- breast cancer cells." (PMID 33861751, 2021).
breast tumor (1 paper, 2021). "In the present study, we examined whether CSNK1G2 was associated with altered sphere-forming ability by TAM in human breast tumor cells." (PMID 33861751, 2021).
Sepsis (1 paper, 2020). Sepsis is defined as life-threatening organ dysfunction caused by a dysregulated host response to infection. "Notably, although the Csnk1g2 knockout mice looked normal, they died within 18 hr after TNF-α administration, much quicker than their wild-type littermates, indicating that TNF-α-induced systematic sepsis was dramatically enhanced." (PMID 33206046, 2020).
tumor (2 papers, 2021 to 2023). "When MCF-7 cells were co-treated with 1 μM TAM and CSNK1G2 silencing, the number of formed tumor spheres was markedly reduced to 15%, compared to that of vehicle-treated cells." (PMID 33861751, 2021). "Since the role of CD44 and CD24 in tumor metastasis and invasiveness has previously been reported, CSNK1G2 may, in part, contribute to tumor progress." (PMID 33861751, 2021). "CSNK1G2 selectively manipulates the tumor progress, sometimes in a nuclear and genomic manner via ERE inhibition of specific genes associated with tumor growth, but sometimes by non-genomic manner via the AKT/mTOR/S6K pathway, followed by p-ER167 activity." (PMID 33861751, 2021).
CSNK1G2 also shares sentences with these, for which no sentence is quoted: cancer (3 papers); anorexia nervosa (1); autism spectrum disorder (1); bulimia nervosa (1); hepatocellular carcinoma (1); pharyngeal cancer (1); type 2 diabetes (1).